SEC24C (SEC24 homolog C, COPII component)
Description:
Component of the coat protein complex II (COPII) which promotes the formation of transport vesicles from the endoplasmic reticulum (ER). The coat has two main functions, the physical deformation of the endoplasmic reticulum membrane into vesicles and the selection of cargo molecules for their transport to the Golgi complex. Plays a central role in cargo selection within the COPII complex and together with SEC24D may have a different specificity compared to SEC24A and SEC24B. May more specifically package GPI-anchored proteins through the cargo receptor TMED10. May also be specific for IxM motif-containing cargos like the SNAREs GOSR2 and STX5.
Synonyms: KIAA0079
Tractability: Antibody: UniProt places it where antibodies can reach, with high confidence. PROTAC: ubiquitination databases record sites on it; its protein half-life has been measured.
Gene: Protein-coding gene on chromosome 10 (73,744,366 to 73,772,173, forward strand). Ensembl gene ENSG00000176986.
Subcellular location: Cytoplasmic vesicle, COPII-coated vesicle membrane; Endoplasmic reticulum membrane; Cytoplasm, cytosol
Subcellular location (Human Protein Atlas): Vesicles
Pathways (Reactome):
Immune System: Antigen Presentation: Folding, assembly and peptide loading of class I MHC; MHC class II antigen presentation
Vesicle-mediated transport: COPII-mediated vesicle transport; Cargo concentration in the ER
Disease: SARS-CoV-2 activates/modulates innate and adaptive immune responses
Metabolism: Regulation of cholesterol biosynthesis by SREBP (SREBF)
Gene Ontology:
Molecular function: cargo adaptor activity; protein binding; SNARE binding; zinc ion binding
Biological process: COPII-coated vesicle cargo loading; endoplasmic reticulum to Golgi vesicle-mediated transport; positive regulation of ER to Golgi vesicle-mediated transport; intracellular protein transport
Cellular component: COPII vesicle coat; cytosol; endoplasmic reticulum membrane; endoplasmic reticulum; ER to Golgi transport vesicle membrane
Genetic constraint (gnomAD): Loss-of-function variants: 22 observed, 114.1 expected, observed/expected ratio (o/e) 0.19, 90% interval 0.14 to 0.28. The upper end of that interval is the gene's LOEUF score, 0.28, which puts it in group 1 of 6, group 1 being the genes least tolerant of losing a copy. Missense variants: 1,149 observed, 1,407.8 expected, observed/expected ratio (o/e) 0.82, 90% interval 0.78 to 0.86. Synonymous variants: 502 observed, 544.56 expected, observed/expected ratio (o/e) 0.92, 90% interval 0.86 to 0.99.
Homologues: Orthologues: chimpanzee SEC24C (99% identical), macaque SEC24C (98% identical), dog SEC24C (95% identical), pig SEC24C (94% identical), mouse Sec24c (92% identical), rat Sec24c (92% identical).
Diseases named in the same sentence as SEC24C in open-access papers:
SEC24C is named in the same sentence as 23 diseases in open-access papers, as found by Europe PMC text mining. Sharing a sentence is not in itself a finding about the gene and the disease. The quoted sentences say what the papers report.
bipolar disorder (2 papers, 2011 to 2014). A disorder of the brain that causes unusual shifts in mood, energy, activity levels and the ability to carry out day-to-day tasks. "Several previously unidentified disease marker genes and drug targets, such as SBNO2 (schizophrenia), SEC24C (bipolar disorder), and SRRT (major depression), were identified based on statistical and topological analyses of the PPI network." (PMID 22373040, 2011). "For example, one study identified a set of disease markers for bipolar disorder that includes SEC24C (involved in vesicular transportation from endoplasmic reticulum to Golgi apparatus) and MUSK (which encodes proteins responsible for receptor assembly in the neuromuscular junction)." (PMID 25202283, 2014). "These genes included SBNO2, CEACAM5, AKAP1, UBC, ACTB, UBB, and FOS for schizophrenia; SEC24C, PGLYRP1, ARHGAP4, RPL22, SLC6A11, and SYK for bipolar disorder; and SRRT, PARK2, LILRA4, STK17A, IGFBP2, and NF1 for major depression." (PMID 22373040, 2011). "Apart from this study, SBNO2, SEC24C and SRRT have never been associated with schizophrenia, bipolar disorder, or major depression; these genes did not form PPI with any of our abnormally expressed marker genes, either." (PMID 22373040, 2011).
depression (2 papers, 2011 to 2021). "Moreover, dysregulation of Sec24c in the Dep-Sus group might affect cell surface levels of the serotonin transporters and thus be linked to depression." (PMID 34603401, 2021).
HIV-1 infection (2 papers, 2021 to 2022). The type species of lentivirus and the etiologic agent of acquired immunodeficiency syndrome (AIDS). "The SEC24C/CA interaction stabilizes the HIV-1 capsid in vitro and in target cells, and SEC24C KO or knockdown leads to a marginal defect in HIV-1 infection, a phenotype comparable to IP5 and IP6 depletion." (PMID 34613803, 2021). "Cellular proteins CPSF6, NUP153 and SEC24C play crucial roles in HIV-1 infection." (PMID 36202818, 2022). "Host proteins CPSF6, NUP153, and SEC24C are vital for HIV-1 infection." (PMID 36202818, 2022).
microcephaly (2 papers, 2023 to 2025). A congenital or acquired developmental disorder in which the circumference of the head is smaller than normal for the person's age and sex. "Although Sec24c-knockout mice die at early embryonic stages, a conditional knockout of Sec24c in mouse neural progenitors causes apoptotic cell death of postmitotic neurons and results in microcephaly and perinatal lethality." (PMID 40131364, 2025). "Ubiquitous loss of murine SEC24C results in early embryonic lethality at approximately E7.5 due to abnormal gastrulation and ectoderm development, while mice with SEC24C deficiency restricted to neural progenitors demonstrate perinatal lethality and microcephaly due to widespread cell death." (PMID 36594468, 2023). "The observation of a critical role of Sec24c in mouse brain development is in line with the observed phenotypes in our patient, especially the severe developmental delay, microcephaly, structural brain anomalies, and seizures." (PMID 40131364, 2025).
adenoma (1 paper, 2017). A neoplasm arising from the epithelium. "The distribution of Sec24C that we observed showed a general increase in adenoma and early CRC stages, while its expression appeared decreased in more advanced CRC stages." (PMID 28344541, 2017).
breast carcinoma (1 paper, 2025). "To elucidate the intricate roles of ADK fusion genes in HR+/HER2‒ breast cancer, we identified several distinct fusion events involving ADK with 6 different partner genes: PCDH15, SEC24C, KAT6B, RSU1, NARS2, and LRMDA." (PMID 41213951, 2025).
Epileptic encephalopathy (1 paper, 2025). A condition in which epileptiform abnormalities are believed to contribute to the progressive disturbance in cerebral function. "Deficiency of SEC24C causes a syndromic epileptic encephalopathy, alters important cellular pathways and causes lens defects, cerebellar anomalies and locomotor defects in a zebrafish model." (PMID 40131364, 2025).
gout (1 paper, 2022). A condition characterized by painful swelling of the joints, which is caused by deposition of urate crystals. "In addition, protein transport protein Sec24C in SF-derived exosomes of axSpA was higher than other groups, while Sec24C in RA, gout, and OA were close." (PMID 35359923, 2022).
melanoma (1 paper, 2022). A malignant, usually aggressive tumor composed of atypical, neoplastic melanocytes. "We first generated Sec24c, Gcc2, Rab14 and Npc1 pooled CRISPR-KO B16 melanoma cells and implanted them in C57BL/6 wild-type mice." (PMID 36379959, 2022).
infection (5 papers, 2021 to 2025). The state of being infected such as from the introduction of a foreign agent such as serum, vaccine, antigenic substance or organism. "There was about a 20% infection reduction with the combined depletion of Sec24c and Sec24d isoforms (p-value 0.0004)." (PMID 40431628, 2025). "Alternatively, disrupting the ability of the capsid to interact with FG-containing cofactors (Sec24C, Nup153, and CPSF6) has also been proposed to inhibit infection." (PMID 38347802, 2024). "Sec24c is nearly identical to CPSF6 in its requirement for infection by diverse lentiviruses, as EIAV and FIV were not affected by Sec24c knockout in contrast to some SIV strains of which infectivity were reduced in cells lacking Sec24c." (PMID 34702294, 2021).
cancer (2 papers, 2018 to 2021). A tumor composed of atypical neoplastic, often pleomorphic cells that invade other tissues. "SEC24C has previously been shown to be phosphorylated by protein kinase B/AKT, which is hyper-activated in cancer; therefore, we analyzed the influence of AKT on SLC6A14 trafficking to the cell surface." (PMID 34359969, 2021).
SEC24C also shares sentences with these, for which no sentence is quoted: anemia (1 paper); Anxiety (1); cataract (1); colorectal cancer (1); congenital cataracts (1); congenital microcephaly (1); developmental delay (1); epilepsy (1); fibrosis (1); Intellectual disability (1); schizophrenia (1); tumour (1).